PSD2 (pleckstrin and Sec7 domain containing 2)
Synonyms: EFA6C; DKFZp761B0514
Tractability: Antibody: UniProt places it where antibodies can reach, with medium confidence; UniProt predicts a signal peptide or a membrane-spanning region; its Gene Ontology location is reachable by antibodies, with medium confidence; the Human Protein Atlas places it where antibodies can reach. PROTAC: its protein half-life has been measured.
Gene: Protein-coding gene on chromosome 5 (139,795,808 to 139,844,470, forward strand). Ensembl gene ENSG00000146005.
Subcellular location: Cell membrane; Cell projection, ruffle membrane; Cleavage furrow
Subcellular location (Human Protein Atlas): Plasma membrane
Gene Ontology:
Molecular function: guanyl-nucleotide exchange factor activity; phospholipid binding
Biological process: regulation of ARF protein signal transduction
Cellular component: cleavage furrow; plasma membrane; ruffle membrane
Genetic constraint (gnomAD): Loss-of-function variants: 36 observed, 66.75 expected, observed/expected ratio (o/e) 0.54, 90% interval 0.41 to 0.71. The upper end of that interval is the gene's LOEUF score, 0.71, which puts it in group 2 of 6, group 1 being the genes least tolerant of losing a copy. Missense variants: 927 observed, 1,038.3 expected, observed/expected ratio (o/e) 0.89, 90% interval 0.85 to 0.94. Synonymous variants: 404 observed, 435.91 expected, observed/expected ratio (o/e) 0.93, 90% interval 0.85 to 1.01.
Homologues: Orthologues: chimpanzee PSD2 (99% identical), macaque PSD2 (98% identical), dog PSD2 (91% identical), guinea pig PSD2 (91% identical), rat Psd2 (89% identical), pig PSD2 (89% identical), mouse Psd2 (88% identical), rabbit PSD2 (76% identical), zebrafish psd2 (59% identical), Drosophila melanogaster siz (15% identical), Drosophila melanogaster Sec71 (14% identical), Drosophila melanogaster garz (14% identical), and 3 more. Paralogues in human: PSD3 (46% identical), PSD (46% identical), PSD4 (35% identical), IQSEC1 (19% identical), MON2 (19% identical), IQSEC3 (17% identical), GBF1 (17% identical), IQSEC2 (17% identical), ARFGEF1 (16% identical), ARFGEF2 (15% identical), CYTH1 (13% identical), CYTH3 (13% identical), and 3 more.
Diseases named in the same sentence as PSD2 in open-access papers:
PSD2 is named in the same sentence as 8 diseases in open-access papers, as found by Europe PMC text mining. Sharing a sentence is not in itself a finding about the gene and the disease. The quoted sentences say what the papers report.
lung carcinoma (1 paper, 2023). "Furthermore, SUGP1 has been recently linked to lung cancer, and PSD2 has been linked to neurological diseases according to GeneCards." (PMID 37298272, 2023).
Obesity (1 paper, 2019). Accumulation of substantial excess body fat. "This involvement is corroborated by genetic studies of body mass index in humans, describing a role played in obesity by the CXXC5 gene in Americans and the PSD2 gene in the Japanese population." (PMID 31199810, 2019).
systemic candidiasis (1 paper, 2022). "Furthermore, mutants lacking either the PS synthase Cho1 or PS decarboxylases (Psd1 and Psd2) were avirulent in murine models of systemic candidiasis and oropharyngeal candidiasis." (PMID 35164565, 2022).
PSD2 also shares sentences with these, for which no sentence is quoted: aneurysm (1 paper); cancer (1); colorectal cancer (1); fungal infections (1); neurological diseases (1).